RBM28 (RNA binding motif protein 28)
Description:
Nucleolar component of the spliceosomal ribonucleoprotein complexes.
Synonyms: FLJ10377; NOP4; ANES
Tractability: PROTAC: UniProt records ubiquitination sites on it; ubiquitination databases record sites on it; its protein half-life has been measured.
Gene: Protein-coding gene on chromosome 7 (128,297,685 to 128,343,971, reverse strand). Ensembl gene ENSG00000106344.
Subcellular location: Nucleus, nucleolus
Subcellular location (Human Protein Atlas): Nucleoli
Pathways (Reactome):
Metabolism of RNA: Major pathway of rRNA processing in the nucleolus and cytosol
Gene Ontology:
Molecular function: protein binding; RNA binding; nucleic acid binding
Cellular component: nucleolus
Genetic constraint (gnomAD): Loss-of-function variants: 71 observed, 95.66 expected, observed/expected ratio (o/e) 0.74, 90% interval 0.61 to 0.9. The upper end of that interval is the gene's LOEUF score, 0.9, which puts it in group 3 of 6, group 1 being the genes least tolerant of losing a copy. Missense variants: 813 observed, 921.62 expected, observed/expected ratio (o/e) 0.88, 90% interval 0.83 to 0.94. Synonymous variants: 298 observed, 339.7 expected, observed/expected ratio (o/e) 0.88, 90% interval 0.8 to 0.97.
Homologues: Orthologues: chimpanzee RBM28 (100% identical), macaque RBM28 (92% identical), pig RBM28 (86% identical), dog RBM28 (86% identical), guinea pig RBM28 (84% identical), rabbit RBM28 (84% identical), mouse Rbm28 (81% identical), rat Rbm28 (75% identical), tropical clawed frog rbm28 (57% identical), zebrafish rbm28 (50% identical), Drosophila melanogaster CG4806 (28% identical), Caenorhabditis elegans sgnh-1 (6% identical), and 2 more. Paralogues in human: CELF2 (15% identical), CELF4 (15% identical), CELF6 (15% identical), CELF1 (14% identical), CELF5 (14% identical), CELF3 (14% identical).
Diseases named in the same sentence as RBM28 in open-access papers:
RBM28 is named in the same sentence as 13 diseases in open-access papers, as found by Europe PMC text mining. Sharing a sentence is not in itself a finding about the gene and the disease. The quoted sentences say what the papers report.
ANE syndrome (2 papers, 2016 to 2017). "Circular dichroism and NMR demonstrate that the ANE syndrome mutation in RRM3 of human RBM28 disrupts domain folding." (PMID 27077951, 2016). "A homozygous missense mutation in the nucleolar protein RBM28 causes the ribosomopathy, alopecia, neurological defects and endocrinopathy (ANE) syndrome." (PMID 27077951, 2016). "This hypomorphism may, in part, explain how the ANE syndrome mutation is compatible with life, as the presence of the mutation leads to a partially functional RBM28 protein." (PMID 27077951, 2016). "ANE syndrome is a ribosomopathy caused by a mutation in an RNA recognition motif of RBM28, a nucleolar protein conserved to yeast (Nop4)." (PMID 27077951, 2016). "Together, these results suggest that the molecular basis of ANE syndrome lies in defective protein folding that reduces protein interactions and the function of RBM28 as a hub protein, resulting in pre-rRNA processing defects in the nucleolus." (PMID 27077951, 2016). "We determined that the molecular pathogenesis of ANE syndrome (L351P in the nucleolar protein, RBM28) results from disrupted RRM3 protein structure that reduces its function as a hub protein in the LSU processome and causes defects in pre-rRNA processing." (PMID 27077951, 2016). "ANE syndrome was classified as a ribosomopathy because RBM28 is localized to the nucleolus and because patient fibroblasts showed reduced numbers of ribosomes." (PMID 27077951, 2016). "A ClustalX alignment of the yeast Nop4 and human RBM28 amino acid sequences permitted identification of the orthologous ANE syndrome mutation in Nop4." (PMID 27077951, 2016). "The main challenges for the future are to find out whether human RBM28 plays a similar role in ribosome assembly as the yeast protein, and to work out how disrupting ribosome assembly could lead to the symptoms of ANE syndrome." (PMID 27077951, 2016). "Indeed, human RBM28 deficiency is not lethal and shows some specific phenotypes including alopecia, mental retardation, progressive motor decline, and hypopituitarism (ANE syndrome)." (PMID 28793857, 2017).
Lung Squamous Cell Carcinoma (1 paper, 2019). "The study reported 141 common AS events between HNSCC and Lung Squamous Cell Carcinoma and 63 out of the 141 splicing events to be associated with RNA binding motif protein 28 (RBM28)." (PMID 31159745, 2019).
schizophrenia (1 paper, 2025). A major psychotic disorder characterized by abnormalities in the perception or expression of reality. "For instance, TF-tagged genes CRABP1, DOK1, RBM28, and C12orf65 are regulated by multiple schizophrenia-related TFs." (PMID 39905509, 2025).
genetic disorder (1 paper, 2023). "In support of this idea, the human gene rbm28, which we found in the NOC1 interactome, is responsible for the ribosomopathy-ane syndrome, a rare genetic disorder caused by aberrant splicing in RBM28 pre-mRNA." (PMID 38213308, 2023).
infection (1 paper, 2023). The state of being infected such as from the introduction of a foreign agent such as serum, vaccine, antigenic substance or organism. "Proteins downregulated during later stages of MVA infection showed a strong tendency to self-associate, including nuclear pore components, and a selection of nucleolar proteins associated with ribosome biogenesis (e.g. SURF6, RBM28, RPL7L1, ZC3HAV1, CDK105)." (PMID 38065956, 2023).
RBM28 also shares sentences with these, for which no sentence is quoted: alopecia (1 paper); anorexia nervosa (1); cancer (1); Cirrhosis (1); depression (1); hypopituitarism (1); liver cirrhosis (1); microcephaly (1).